LEP (leptin)
Diseases named in the same sentence as LEP in open-access papers (continued):
Sharing a sentence is not in itself a finding about the gene and the disease.
Obesity (continued). "Obesity is recognized as an important contributing factor to numerous types of cancers, including breast cancer, which is associated with increased leptin secretion." (PMID 38791252, 2024). "Leptin and adiponectin are the two major protein hormone secreted by white adipose tissue, that have a preventive role against obesity and dementia, and both are involved in the causal relationship between obesity and cognitive decline." (PMID 39273520, 2024). "Inflammation associated with obesity leads to leptin resistance and reduced secretion of lipocalin and induces neurodegeneration in the brain and the development of diseases associated with neurodegenerative disorders, including AD." (PMID 38334839, 2024). "Obesity causes hyperleptinemia (elevated plasma leptin levels) in humans and mice, which is associated with preeclampsia." (PMID 39201703, 2024). "In general, the ready availability of genetic diagnostics in Western countries, which, according to the Endocrine Society guidelines should be performed in all patients with severe early onset of obesity, will identify leptin variants of all CLD subtypes." (PMID 38470203, 2024). "In this study, we directly observed the process of obesity developing into hepatic steatosis and hepatitis using an ob/ob mouse model that induces obesity due to mutation of the leptin gene." (PMID 39594477, 2024). "The influence of leptin on GABA neurons in the cerebral cortex has also been implicated in the prevention of obesity." (PMID 39478699, 2024). "Beyond enhancing energy consumption in target cells, leptin can promote the production of pro-inflammatory cytokines, underlying the inflammatory and painful impacts of obesity." (PMID 38532900, 2024). "Although leptin is not alone in controlling energy balance, its crucial role is evidenced by the excessive obesity, hyperphagia, and infertility of the leptin-deficient ob/ob mouse." (PMID 38131197, 2024). "Obesity is associated with increased levels of leptin, which has only very limited effects due to tissue resistance to leptin associated with insulin resistance and abdominal obesity." (PMID 38398863, 2024). "Rare monogenic obesity primarily involves gene defects related to the leptin-melanocortin pathway, such as the LEP gene encoding leptin, the LEPR gene encoding leptin receptors, and SH2B1." (PMID 39232780, 2024). "Leptin resistance is an unclearly defined and not fully understood state of impaired leptin function linked to food intake and is commonly seen in cases of obesity." (PMID 39232748, 2024). "The reduction in Clostridium sensu stricto, linked to obesity and elevated plasma leptin levels, suggests a gut-flora-mediated mechanism in limiting BW gain." (PMID 39765737, 2024). "Cesarean births have also been associated with lower rates of early breastfeeding and reduced umbilical leptin concentrations, both of which have been linked to an increased risk of developing obesity later in life." (PMID 39401190, 2024). "Obesity is also associated with elevated leptin levels, which have been linked to both osteogenic and osteolytic effects in animal models." (PMID 39902393, 2024). "Elevated systemic pro-inflammatory markers like C-reactive protein, TNF-α, TGF-β, leptin, and IL-6 are linked to the obesity." (PMID 38762465, 2024). "Recent study conducted in a high-fat diet mouse model revealed that partial leptin deficiency prevented the upregulation of leptin levels, consequently leading to the protection of mice against diet-induced obesity and metabolic disorders." (PMID 40302954, 2024). "Disruptions in lipid metabolism within the liver play a pivotal role in the development of obesity, and leptin has been implicated in liver function." (PMID 38623207, 2024). "Obesity is linked to elevated leptin levels and leptin resistance, which impairs the hormone’s ability to regulate satiety." (PMID 40474934, 2024).
Obesity (continued). "High levels of ARA-containing lipid species were also documented in leptin-deficient mouse obesity models." (PMID 38965596, 2024). "Because obesity is associated with an up-regulation of pro-inflammatory cytokines and/or increased production of leptin, low-grade systemic inflammation is likely detrimental to bone health." (PMID 38473961, 2024). "Leptin, as a proinflammatory adipokine, is known to be associated with obesity-related inflammation." (PMID 38464534, 2024). "Leptin signaling plays a crucial role in developing obesity and insulin resistance, the genetic model db/db mice with lepr mutation was developed to model the leptin signaling deficiency in T2DM." (PMID 39484619, 2024). "Leptin-deficient mice develop obesity, and fatty livers due to inherent deficiency of the appetite-suppressing hormone, leptin." (PMID 38237682, 2024). "Cortisol can promote obesity by influencing leptin sensitivity and insulin resistance, and the abnormally high cortisol in plasma cause abnormal obesity and Cushing’s syndrome." (PMID 38467615, 2024). "Forms of leptin have been created and investigated to reverse obesity, but promising effects were seen only in leptin-deficient pathologies." (PMID 39125635, 2024). "On the other hand, non-syndromic Mendelian obesity forms identified thus far are primarily associated with genetic defects in the leptin/melanocortin pathway, leading to hyperphagic obesity." (PMID 39045266, 2024). "Mutations in the gene encoding leptin can lead to severe obesity in both animals and humans, with severe obesity potentially resulting in telomere shortening." (PMID 38615017, 2024). "Most of the genes involved in the pathogenic variants were linked to obesity-related ciliopathies (7/11, 64%), followed by the leptin signaling pathway (2/11, 18%) and cell-signaling regulation genes (2/11, 18%)." (PMID 38674329, 2024). "Specifically, CLOCK/CC, FTO/AA, and LEP/AA genotypes were strongly associated with higher obesity metrics and emotional eating scores, while GHRL/TT and MC4R/CC were linked to increased BMI and WHR." (PMID 39203789, 2024). "Adiponectin and leptin, hormones secreted by adipocytes, regulate low-grade inflammation caused by obesity." (PMID 39685854, 2024). "Of the 607 obesity-associated genes in our study, 120 have been found to be associated with adiposity in previous studies, such as the LEP gene encoding the adipokine leptin and several cytokines of the interleukin and tumor-necrosis-factor alpha families." (PMID 35953519, 2024). "Concurrently, the resultant leptin resistance associated with obesity can adversely affect various peripheral tissues, including the liver, pancreas, platelets, vasculature, and myocardium." (PMID 38397015, 2024). "Leptin, which exerts its effects in early life, has the potential to influence the risk of obesity later in life." (PMID 39224127, 2024). "It is well established that adipokines, mostly leptin and adiponectin, and the ratio leptin/adiponectin (L/A), are associated significantly with the development of obesity and insulin resistance." (PMID 38255954, 2024). "Further complexity regarding the role of leptin in energy feedback was uncovered in a model of mouse obesity caused by forced overfeeding, with leptin levels “clamped” at normal levels and unable to rise." (PMID 38165042, 2024). "Some other genetic variants linked to obesity are found within the genes of biomarkers described in the previous section, such as in the leptin, leptin receptor, or adiponectin." (PMID 38474344, 2024). "In animal models, the targeted deletion of leptin is associated with obesity, type II diabetes, and infertility." (PMID 38339144, 2024). "Maternal obesity during pregnancy increases the risk of offspring developing obesity, and obesity is characterized by elevated levels of leptin in pregnant females." (PMID 38572473, 2024).
Obesity (continued). "Circulating leptin is directly associated with body fat and is involved in appetite regulation, energy homeostasis, and obesity-related proinflammatory status." (PMID 38289144, 2024). "On the other hand, in adipocytes, IL-6 induces the release of FFAs and leptin and blunts obesity-associated metabolic complications." (PMID 38544694, 2024). "Obesity is associated with increased ovarian inflammation and the establishment of leptin resistance." (PMID 38580672, 2024). "Increased leptin in obesity is also associated with leptin resistance in the central nervous system, which decreases its anorexigenic effects despite its high peripheral concentration." (PMID 39593945, 2024). "The history of leptin begins with the identification of the gene responsible for obesity, the obese gene, LEP, which encodes 16-kDa leptin." (PMID 39057043, 2024). "Although copper is essential for the breakdown of fat cells, high blood copper levels are associated with obesity, and serum copper levels are positively correlated with BMI, leptin, and insulin." (PMID 37132140, 2024). "Data on adipose tissue biology in CDAA-HFD are scarce, but increased expression and release of the obesogenic cytokine leptin is considered a hallmark of severe obesity and the metabolic syndrome." (PMID 39361025, 2024). "A previous prospective RCT demonstrated that a reduction of 3.3 ng/mL in leptin levels over one month is a strong predictor of long-term weight loss in adults with overweight and obesity." (PMID 38178093, 2024). "Chronic inflammation caused by obesity inhibits the effects of leptin on the central nervous system, and leptin is not only an anti-obesity hormone, but also possesses an antidepressant effect." (PMID 39564461, 2024). "In light of this extensive research, the aim of the present study was to elucidate the effects of obesity on lipid metabolism and mitochondrial function in the livers of leptin-deficient mice while assessing the therapeutic potential of melatonin." (PMID 39201365, 2024). "TRH is known as the primary regulator of the hypothalamic-pituitary-thyroid axis, which is important for maintaining energy expenditure and body weight and is active even in states of leptin resistance associated with obesity." (PMID 38577975, 2024). "Neuroinflammation can lead to leptin resistance and feeding behavior disorder to induce obesity, which implies that obesity is also associated with inflammatory signaling in the brain-gut axis." (PMID 38932932, 2024). "It is currently believed that obesity in these diseases is associated through the leptin–melanocortin pathway influencing the hypothalamus." (PMID 39126056, 2024). "Patients with leptin deficiency have been observed to develop obesity and hyperphagia in childhood, prompting the consideration of leptin replacement therapy to suppress appetite and increase energy expenditure." (PMID 38397015, 2024). "The Lep ob/ob mouse model is a genetic model of MetS backcrossed to the C57BL/6J strain that is homozygous for a spontaneous obesity mutation in the Leptin (Lep) gene leading to a deficiency in the functional leptin protein." (PMID 39452073, 2024). "Obesity in dogs is also associated with an increase in leptin following a meal and with decreased postprandial response of dietary carnitine, perhaps due to altered fat metabolism." (PMID 39057696, 2024). "This was followed shortly after by the identification of the first monogenic cause of human obesity, congenital leptin deficiency, and its successful treatment with recombinant human leptin." (PMID 38019584, 2024). "Obesity in the leptin-deficient ob/ob mice is associated with fatty livers due to the accumulation of triglycerides in the hepatocytes, which imposes considerable metabolic stress to the cells." (PMID 38992049, 2024).
Obesity (continued). "We used 2 separate obesity models to delineate the effects of obesity per se from consumption of a high-calorie diet: diet-induced obese animals and leptin-deficient Ob/Ob animals (fed a chow diet)." (PMID 38833481, 2024). "Recombinant leptin treatment provides an effective mean to reduce obesity in leptin-deficient individuals." (PMID 39872218, 2024). "The concentration of circulating leptin in the blood is high in obese patients, and chronic leptin secretion caused by obesity can induce leptin resistance." (PMID 38392211, 2024). "Out of the thirty-three genes for which selected genetic variants were reported as significantly associated with obesity, only four genes (LEP, LEPR, POMC, and MC4R) are known to be linked with monogenic obesity." (PMID 39457458, 2024). "Although db/db mice are suitable for obesity and T2DM research, leptin mutations result in extreme obesity and diabetes symptoms, leading to significant phenotypic changes that make it challenging to understand the progression stages of human diseases." (PMID 39050759, 2024). "Human research focused on biomarkers (risk factors, adipokines [like leptin], intercellular signaling peptides [like fibronectins]), and complications of obesity (insulin resistance, inflammation, and metabolic syndrome)." (PMID 39376657, 2024). "Leptin signaling-deficient model of steatosis, diabetes and obesity (ob/ob and db/db mice) displayed a similar increase in hepatic miR-149-5p expression." (PMID 39263327, 2024). "In rats, simultaneous exogenous administration of leptin and amylin leads to weight loss, although, in more severe obesity, their synergistic effect was less prominent." (PMID 38338796, 2024). "Investigating potential treatments and associated mechanisms to restore leptin sensitivity is crucial for effective obesity management." (PMID 38623207, 2024). "Obesity is known to cause chronic metabolic dysfunction, resulting in altered levels of insulin/glucose, leptin/adiponectin, and other hormones and adipokines in the blood." (PMID 38311726, 2024). "In conclusion, our study reveals a feedback loop between TET2 and leptin, which enables adipocytes to coordinate the hyperleptinemia associated with obesity." (PMID 38561362, 2024). "The adiponectin-to-leptin (A/L) ratio is considered an indicator of adipose tissue dysfunction, with a lower ratio being associated with an increased risk of obesity-related diseases." (PMID 38339282, 2024). "This review highlights the importance of genetics in obesity, discussing cases of syndromic obesity such as Prader–Willi and Bardet–Biedl and of common monogenic obesity that are mainly characterized by mutations in the leptin–melanocortin pathway." (PMID 38397265, 2024). "Establishing a panel of biomarkers, such as cocaine/amphetamine-regulated transcript (CART) and leptin, improves the comprehension of the underlying mechanisms related to appetite, energy expenditure, and obesity." (PMID 38398459, 2024). "Obesity is associated with higher leptin levels, lower adiponectin levels, and a higher leptin/adiponectin (L/A) ratio." (PMID 39000449, 2024). "Many factors contribute to the development of obesity in DS as high serum leptin levels, genetic susceptibility, hypothyroidism, low physical activity, increased serum lipids, and an abnormal diet." (PMID 39706986, 2024). "Leptin is widely recognized as a cytokine, pleiotropic hormone, and an obesity-associated adipokine that upon binding to its leptin receptor, regulates energy metabolism and appetite." (PMID 38418632, 2024). "An increased leptin concentration in blood is associated with insulin resistance and obesity in T2DM individuals." (PMID 38254166, 2024). "Mutations in LEPR can cause receptor deficiency, leading to severe obesity and hyperphagia due to improper leptin signaling." (PMID 39777073, 2024).
Obesity (continued). "Elevated levels of circulating leptin are generally attributed to the development of leptin resistance, a hallmark of obesity, which is already recognized as a risk factor for severe COVID-19." (PMID 39175753, 2024). "Our findings demonstrate that increased leptin levels are associated with increased risk of diabetes or obesity, compared with population control subjects." (PMID 39684379, 2024). "This study aimed to explore the therapeutic potential of acupoints catgut embedding (ACE) in addressing obesity and its associated leptin resistance." (PMID 38623207, 2024). "Adipokines, such as leptin and adiponectin, secreted from adipose tissue also have a significant association in obesity pathogenesis and its metabolic complication." (PMID 39000449, 2024). "In contrast to the reported obesity-associated leptin resistance, central IL-6 trans-signaling appears to be stimulated in obesity." (PMID 39723211, 2024). "Leptin and adiponectin, two hormones associated with obesity, play crucial roles in brain function and are linked to both obesity and depression." (PMID 39335507, 2024). "Given that WC and WHR are useful predictors of abdominal obesity, this study highlights the potential role of the CLOCK, FTO, and LEP gene variants in increasing the risk of this type of obesity, which is often associated with cardiovascular disease." (PMID 39203789, 2024). "In this study, we found regulation of sAPPα levels in the media by leptin, a widely recognized obesity-associated adipokine that has recently been shown to play a possible role in cancer signaling." (PMID 38418632, 2024). "It has been demonstrated that obesity-induced inflammation in the hypothalamus causes cellular resistance to insulin and leptin, resulting in problems of the hypothalamus’ function to regulate the homeostatic appetite system." (PMID 39266589, 2024). "Leptin levels are elevated in individuals with obesity and are associated with leptin resistance, which is related to various metabolic diseases." (PMID 39444577, 2024). "Leptin-deficient ob/ob mice are hyperphagic and develop severe obesity, insulin resistance, and steatosis." (PMID 39337328, 2024). "In our present study, we identified compound heterozygous mutations (c.350G > A, c.451C > T) in the LEP gene within an obesity-related family, exhibiting a loss-of-function feature." (PMID 39041042, 2024). "Overall obesity also demonstrated causal links with insulin resistance, circulating leptin levels, C-reactive protein levels and risk of severe insulin resistant type 2 diabetes." (PMID 38977823, 2024). "Our data showed that both global and adipocyte-specific Tet2 deficiency protected against HFD-induced obesity in tandem with increased energy expenditure and decreased food intake, indicating an increase in leptin sensitivity." (PMID 38561362, 2024). "Congenital leptin deficiency in mouse models (ob/ob) and in humans is characterised by undetectable serum leptin and early-onset severe obesity associated with intense hyperphagia." (PMID 39002670, 2024). "Obesity is linked to an increase in leptin levels, potentially resulting in hypothalamic leptin resistance and a reduction in GnRH pulsatile amplitude and LH levels." (PMID 38737557, 2024). "Dysregulation of the central leptin axis is considered a main cause of obesity, but in humans it is primarily overeating that rapidly increases blood leptin levels, leading to leptin resistance and weight gain." (PMID 39317805, 2024). "A small proportion of individuals with obesity are affected by genetic forms of obesity, which often relate to mutations in the leptin-melanocortin pathway or are part of syndromes such as the Bardet-Biedl syndrome." (PMID 39777073, 2024). "In both obesity and AD scenarios, insufficient leptin action is a marked risk factor for neurodegenerative progression." (PMID 38933275, 2024). "Several studies have been carried out to determine the association between leptin levels and obesity or diabetes." (PMID 39684379, 2024).